CDKN2A (cyclin dependent kinase inhibitor 2A)
Diseases named in the same sentence as CDKN2A in open-access papers (continued):
Sharing a sentence is not in itself a finding about the gene and the disease.
kidney clear cell carcinoma (8 papers, 2015 to 2025). "The expression of CDKN2A showed a significant association with the level of immune infiltration in clear cell renal cell carcinoma." (PMID 36588699, 2022). "This is consistent with our finding of recurrent CDKN2A and CDKN2B deletions in CIMP+ samples from KIRC patients mentioned earlier, which were independently linked to a more clinically aggressive phenotype of kidney clear cell carcinoma." (PMID 25960768, 2015).
mucinous ovarian cancer (8 papers, 2018 to 2025). An invasive malignant neoplasm that arises from the ovary and is characterized by the presence of malignant epithelial cells that contain intracytoplasmic mucin and may resemble the epithelial cells of the endocervix or gastrointestinal tract. "Mucinous ovarian carcinomas are associated with the copy number loss of CDKN2A and KRAS mutations, both of which are believed to be early events in tumorigenesis as they have been identified in benign and borderline mucinous precursor neoplasms." (PMID 37370967, 2023). "The largest study of ovarian mucinous carcinomas confirmed frequent copy number losses (hetero- or homozygous) of CDKN2A and mutations in CDKN2A and KRAS as early events." (PMID 35053578, 2022). "In ovarian mucinous tumors, cyclin dependent kinase inhibitor 2A (CDKN2A) and KRAS mutations represent the most common genetic alterations in both ovarian mucinous adenocarcinoma and their precursor lesions." (PMID 40936753, 2025). "Analyses of focal copy number changes revealed amplifications of CCND1 and ERBB2 and homozygous deletions of CDKN2A/B in mucinous ovarian carcinomas, a finding consistent with previous studies." (PMID 40981433, 2025). "Similarly, mutations in CDKN2A and KRAS are commonly found in mucinous ovarian carcinomas as an early event in tumourigenesis, but are not required for diagnosis." (PMID 37370967, 2023).
mucosal (8 papers, 2013 to 2025).
oropharyngeal tumors (8 papers, 2017 to 2023). "We previously reported a novel association between CDKN2A nonpromoter methylation and transcription (ARF/INK4a) in human papillomavirus associated oropharyngeal tumors." (PMID 28102032, 2017).
penile squamous cell carcinoma (8 papers, 2008 to 2024). "Although numbers are very low, results from research on CDKN2A imutations in vulvar and penile squamous cell carcinoma strengthen this hypothesis." (PMID 24671188, 2014).
prostate tumors (8 papers, 2011 to 2025). "Results regarding the frequency of CDKN2A promoter methylation are inconsistent in prostate tumors, ranging from 3% to 77%; other studies have investigated the role of hypermethylated CDKN2A in the carcinogenesis and progression of PCa." (PMID 22547956, 2011). "Moreover, the DNA methylation of the CDKN2A promoter was a more frequent event in aggressive prostatic tumors with PNI." (PMID 37240283, 2023).
cervical adenocarcinoma (7 papers, 2004 to 2022). An adenocarcinoma arising from the cervical epithelium. "However, HeLa cells might not respond to a rising CDKN2A level to a large extent, since mutations in the retinoblastoma gene are not involved in the tumorigenesis of this cervical adenocarcinoma cell line." (PMID 35444189, 2022).
diabetic kidney disease (7 papers, 2019 to 2025). Progressive kidney disorder caused by vascular damage to the glomerular capillaries, in patients with diabetes mellitus. "In glomerular diseases, nuclear CDKN2A levels are elevated in glomerular and interstitial cells and increased in tubular and podocytes in diabetic nephropathy." (PMID 39963130, 2025).
follicular lymphoma (7 papers, 2017 to 2023). Follicular lymphoma is a form of non-Hodgkin lymphoma characterized by a proliferation of B cells whose nodular structure of follicular architecture is preserved. "The loss or methylation of CDKN2A is relatively common in pretreatment follicular lymphoma biopsy specimens and correlated with poor outcome." (PMID 36845727, 2023).
gestational diabetes (7 papers, 2018 to 2026). Carbohydrate intolerance first diagnosed during pregnancy. "In Japanese populations, the gestational-diabetes-related loci include adiponectin (ADIPOQ), CDKN2A/2B, signal sequence receptor subunit 1-Ras-responsive element binding protein 1 (SSR1-RREB1), and MyoD family inhibitor domain-containing 2 (MDFIC2)." (PMID 40650275, 2025).
Human Papillomavirus Infection (7 papers, 2013 to 2021). "In the case of p16INK4A immunohistochemistry (IHC), false positives occur in human papillomavirus infection or when the CDKN2A locus is mutated." (PMID 34916607, 2021).
invasive breast carcinoma (7 papers, 2014 to 2026). A carcinoma that infiltrates the breast parenchyma. "Overexpression of DCAF13, DNMT3B, KPNA2, EXO1, FANCI, RACGAP1, and ZNF106 in invasive breast carcinoma patients showed poor survival, while overexpression of CDKN2A, SORBS1, and TP63 showed better survival." (PMID 32010179, 2019). "On chromosome 9 are located the tumor suppressor genes CDKN2A, PIPSK1B, BTEB1, RECK and BAG1, the latter associated with antiapoptotic functions and overexpressed in invasive breast carcinomas." (PMID 27325915, 2016). "Using TCGA expression data for invasive breast cancer, ANRIL and CDKN2A (p14ARF and p16INK4a combined) were positively correlated (Pearson correlation 0.588), with a marginal positive correlation between ANRIL and p15INK4b (Pearson Correlation 0.39)." (PMID 26835415, 2015).
myxofibrosarcoma (7 papers, 2014 to 2025). A malignant fibroblastic neoplasm arising from the soft tissue. "The author proposed that the variation in growth rate and invasiveness may be partly explained by the presence of mutations in cell cycle checkpoint genes, such as CDKN2A, which is found to be mutated in approximately 16% of myxofibrosarcoma cases." (PMID 37686615, 2023). "A faster growth rate and invasiveness could result from the loss of this tumor suppressor CDKN2A in a patient-derived myxofibrosarcoma." (PMID 37686615, 2023). "A case report of a patient with advanced chemotherapy-refractory myxofibrosarcoma harboring RAF1 S259P mutation and CDKN2A/B loss showed complete radiological response on treatment with MEK inhibitor Trametinib and CDK4/6 inhibitor Palbocilib." (PMID 40556788, 2025). "A recent unique case report described clinical improvement in a patient with myxofibrosarcoma harboring a RAF1 S259P mutation and CDKN2A/Bloss who was treated with a combination of the MEK inhibitor trametinib and the CDK4/6 inhibitor palbociclib." (PMID 41200607, 2025).
osteoporosis (7 papers, 2012 to 2025). A condition of reduced bone mass, with decreased cortical thickness and a decrease in the number and size of the trabeculae of cancellous bone (but normal chemical composition), resulting in increased fracture incidence. "Targeting this TGF‐β‐oxidative‐stress‐cellular senescence pathway by inhibition of TGF‐β signaling, antioxidant treatment, or Cdkn2a inactivation can ameliorate the osteoporosis phenotype in GO." (PMID 39234801, 2024). "Inactivation of Cdkn2a in the GorabPrx1 rescued the osteoporosis phenotype." (PMID 39234801, 2024). "The P16(INK4A) protein encoded by CDKN2A is a typical marker of cellular senescence- release of senescent cells and inflammatory factors involved in the progression of osteoporosis." (PMID 37214253, 2023). "It showed that in osteoporosis patients, CP (P < 0.01), LIPT1 (P < 0.05), SLC25A3 (P < 0.001), and UBE2D3 (P < 0.01) were upregulated, while the expression levels of CDKN2A (P < 0.05), DBH (P < 0.01), DLST (P < 0.05), LOXL2 (P < 0.05), SLC31A1 (P < 0.05), and UBE2D1 (P < 0.01) were downregulated." (PMID 40980812, 2025).
pituitary tumor (7 papers, 2008 to 2022). A benign or malignant neoplasm affecting the pituitary gland. "CDKN2A methylation has been related to the pituitary tumor volume, grade, and patients’ age, with higher methylation levels in macroadenomas." (PMID 35432200, 2022). "It has been demonstrated that CDKN2A methylation occurs in the entire locus, in all subtypes and pituitary tumors." (PMID 28382019, 2017).
plasmacytoma (7 papers, 2006 to 2020). Plasmacytoma is a localized mass of neoplastic monoclonal plasma cells that represents approximately 5% of all plasma cell neoplasms. "Long-term genetic studies utilizing backcross and congenic strain analyses coupled with positional cloning strategies and functional studies identified Cdkn2a, Mtor, and Mndal as mouse plasmacytoma susceptibility/resistance genes." (PMID 32923678, 2020). "Pctr1 and Pctr2 have been mapped as loci for susceptibility to pristine induced plasmacytoma, and Cdkn2a has been suggested to be a corresponding gene for Pctr1." (PMID 17598916, 2007). "While SHP1 and CDKN2A were hypermethylated in both plasmacytomas, CDH1 hypermethylation was detected only in the chest wall." (PMID 30572945, 2018).
synovial sarcoma (7 papers, 2017 to 2025). "In contrast, synovial sarcomas (SS) frequently exhibit overexpression of CDK2, CDK4, and MDM2, loss of CDKN2A, and mutations in genes such as CDK 4/6." (PMID 38275873, 2024). "CDKN2A deletion is a highly frequent event in synovial sarcomas; moreover, the translocation facilitates repression of CDKN2A activity and increases the expression of CDK4 as well as multiple cyclins (D1, B1, A2, I, and F)." (PMID 36741019, 2023). "HDAC inhibitors dissociate the driving complex and reactivate EGR1 and p16INK4a/p14ARF (CDKN2A) expression in synovial sarcoma; we confirm this occurs with treatment by quisinostat, a newer HDAC inhibitor that was the top hit in our compound screen." (PMID 28056055, 2017).
T-cell acute lymphoblastic leukemia (7 papers, 2009 to 2024). Acute lymphoblastic leukemia of T-cell origin. "Additionally, somatic alterations in cyclin-dependent kinase inhibitor 2A (CDKN2A), particularly deletions, are highly prevalent in T-cell ALL (T-ALL) and B-cell ALL (B-ALL) cases, occurring in 78% and 42%, respectively, in contrast to solid tumors where they are present in 11% or less of cases." (PMID 38927907, 2024).
biliary tract cancer (6 papers, 2020 to 2026). "In biliary tract cancers, CDKN2A and CDKN2B alterations in the cell cycle pathway were observed; however, these are not effective therapeutic target genes." (PMID 38672586, 2024).
bladder tumors (6 papers, 2020 to 2025). "We show that bladder tumors developing after pelvic radiation are associated with distinct mutational signatures, which, along with CDKN2A loss and a history of smoking or a smoking-related mutational signature, have a poor prognosis." (PMID 39113632, 2024). "RT-associated bladder tumors were significantly enriched for alterations in KDM6A and ATM, whereas CTRL tumors were enriched for CDKN2A mutation." (PMID 39113632, 2024). "This epigenetic silencing of CDKN2A is especially noteworthy in the context of aging: while normal elderly cells rely on CDKN2A upregulation to enforce senescence, bladder tumor cells can epigenetically shut down CDKN2A expression, thus evading an age-imposed growth arrest." (PMID 40918525, 2025).
chronic pancreatitis (6 papers, 2003 to 2025). A chronic inflammatory process causing damage and fibrosis of the pancreatic parenchyma. "A large-scale study of chronic pancreatitis tissues showed that, in addition to mutations, a hypermethylation of the CDKN2A/p16 gene promoter in PanIN1 stage leads to its inactivation." (PMID 41375051, 2025). "In another word, CDKN2A changes, especially promoter hypermethylation might imply high-risk precursors in chronic pancreatitis that might develop to cancer." (PMID 26338139, 2015). "A meta-analysis including data from more than 500 PDAC, PanINs, and chronic pancreatitis patients between 2002 and 2012, revealed that methylation of the CDKN2A gene plays a crucial role in the development of PDAC." (PMID 41375051, 2025).
ductal adenocarcinomas (6 papers, 2006 to 2022). "The CDKN2A gene (chromosome 9p) is the most commonly inactivated tumor suppressor gene, targeted in 95% of ductal adenocarcinomas." (PMID 36081557, 2022).
emphysema (6 papers, 2009 to 2024). "Gene expression profiling of lung from emphysema patients identified seven candidate genes associated with emphysema severity including COL6A3, SERPINF1, ZNHIT6, NEDD4, CDKN2A, NRN1 and GSTM3." (PMID 19723343, 2009). "The candidate genes (CDKN2A, GSTM3, COL6A3, SERPINF1, NRN1, NEDD4 and ZNHIT6) had ontologies that were relevant to emphysema progression, including cell cycle regulation (CDKN2A), collagen (COL6A3), anti-angiogenesis (SERPINF1) and oxidative stress (GSTM3)." (PMID 19723343, 2009).
follicular carcinoma (6 papers, 2006 to 2024).
gastric tumors (6 papers, 2010 to 2025). "Several cancers, including gastric tumors, show methylation of multiple genes including E-cadherin (CDH1), death-associated protein kinase (DAPK) and cyclin-dependent kinase inhibitor 2A (CDKN2A)." (PMID 23280118, 2013). "It has been shown that there are different patterns of protein expression between cardia and non-cardia carcinoma in terms of several markers, such as CD44, Mucin 1 (MUC1), and Cyclin-Dependent Kinase Inhibitor 2A (CDKN2A)." (PMID 35096085, 2022).
gastrointestinal stromal tumor (6 papers, 2016 to 2024). "For gastrointestinal stromal tumor, the prevalence of the KIT mutation was similar between the two groups, but our cohort had a significantly higher prevalence of CDKN2A and NF1." (PMID 32373528, 2020). "Case 2 (patient ID 501) is a 68-year-old man with metastatic gastrointestinal stromal tumor with BRAF V600E and CDKN2A alterations, who presented after the tumor progressed on BRAF/MEK-targeted therapy." (PMID 33427211, 2021).
laryngeal squamous cell carcinoma (6 papers, 2017 to 2025). A squamous cell carcinoma that arises from the larynx. "However, contrary to this, earlier studies in laryngeal squamous cell carcinoma found an increased frequency of CDKN2A gene hypermethylation in patients at the G3 stage." (PMID 40256740, 2025). "In this study we assessed whether nonpromoter CDKN2A methylation in laryngeal squamous cell carcinomas (LXSCC) conferred a similar association with transcription that predicted patient outcome." (PMID 28102032, 2017).
lupus (6 papers, 2014 to 2024). "However, a recent study found Cdkn2a hypomethylation and expression alterations in systemic lupus erythematosus and systemic sclerosis indicating that Cdkn2a regulation of IFN production is linked to additional syndromes." (PMID 35324997, 2022). "In assessing similarities to other interferonopathies, a genome-wide association study has identified IFN-related genes in lupus, but not the Cdkn2a gene." (PMID 35324997, 2022).
mucinous adenocarcinoma (6 papers, 2014 to 2023). An invasive adenocarcinoma composed of malignant glandular cells which contain intracytoplasmic mucin. "Mucinous carcinomas are uncommon tumors associated with copy-number loss of CDKN2A and KRAS alterations and metastasis from other sites should always be considered in the differential diagnosis." (PMID 33919741, 2021). "In tumors, we found that compared with adenocarcinoma, PDHA1 and GLS were expressed at low levels in mucinous adenocarcinoma, while CDKN2A was highly expressed." (PMID 36246586, 2022).
Pleural effusion (6 papers, 2017 to 2025). The presence of an excessive amount of fluid in the pleural cavity. "Regarding MPM-diagnosis, the use of fluorescence in situ hybridization to detect the homozygous deletion of CDKN2A proved helpful to distinguish between malignant mesothelial cells and benign reactive mesothelial cells both in pleural effusion and tissue samples." (PMID 29371938, 2017).
progeria (6 papers, 2017 to 2024). "One study has shown that treatment with a HSP90 inhibitor (alvespimycin) for one week reduces the senescence marker p16INK4a/Cdkn2a by 60% in mouse kidneys with accelerated ageing (progeroid syndrome)." (PMID 38391050, 2024).
renal fibrosis (6 papers, 2022 to 2025). A final common manifestation of a wide variety of chronic kidney diseases characterized by glomerulosclerosis and tubulointerstitial fibrosis. "No toxicity or alteration in levels of renal fibrosis was seen in uninjured control kidneys treated with Loc14 versus vehicle, and inhibition did not affect senescent cell number, as measured by Cdkn1a or Cdkn2a via qPCR or P21CIP1 expression on immunofluorescence." (PMID 36509292, 2022).